AKR1B10 (aldo-keto reductase family 1 member B10)
Diseases named in the same sentence as AKR1B10 in open-access papers (continued):
Sharing a sentence is not in itself a finding about the gene and the disease.
diabetes (7 papers, 2010 to 2023). "As an exemplar of use as a non-invasive diagnostic, logistic regression establishes a composite model comprising four proteins (ADAMTSL2, AKR1B10, CFHR4 and TREM2), body mass index and type 2 diabetes mellitus status, to identify at-risk steatohepatitis." (PMID 37037945, 2023). "In fact, plenty of current studies aimed to find selective inhibitors for AKR1B1 over AKR1B10, and vice versa, in order to exclusively treat complications of diabetes or cancer." (PMID 29532688, 2018). "Because lens transparency was maintained in AKR1B10 transgenic mice following 6 months of experimental diabetes, we conclude that AKR1B10 has a limited role in the pathogenesis of cataract in human patients with diabetes." (PMID 20628518, 2010). "We employed a genetic strategy to determine if AKR1B10 contributes to the pathogenesis of diabetic cataract in a mouse model." (PMID 20628518, 2010). "AKR1B10 was found to be involved in signaling pathways in diabetes, obesity and atopic dermatitis, probably because AKR1B10 is closely associated with the conversion of glycans and lipids in the organism, and in addition is one of the triggers of cytokine storms." (PMID 37723557, 2023). "The current study also addressed the question of whether AKR1B10 contributes to the onset and progression of cataracts in a mouse model of diabetes." (PMID 20628518, 2010). "AKR1B10 expression has also been observed in nonmalignant disease conditions including atopic dermatitis, diabetes, and leprosy." (PMID 37189628, 2023). "Lenses from transgenic mice designed for overexpression of AKR1B10 were not significantly different from nontransgenic controls, although a significant number developed a focal defect in the anterior lens epithelium following 6 months of experimentally induced diabetes." (PMID 20628518, 2010).
nasopharyngeal carcinoma (7 papers, 2016 to 2024). A carcinoma arising from the nasopharyngeal epithelium. "The low expression of AKR1B10 has also been described as an independent prognostic factor in nasopharyngeal cancer, hinting a tumor suppressive role in this malignancy." (PMID 35280770, 2022). "AKR1B10 protein levels were examined in 51 benign specimens, 238 para-carcinoma specimens and 299 nasopharyngeal cancer specimens by immunochemistry." (PMID 26949513, 2016). "The percentage of AKR1B10-positive specimens was 44.5 % (133/299) in the nasopharyngeal cancer tissue compared with 82.4 % (42/51) in benign specimens (p < 0.01) and 98.7 % (235/238) in para-carcinoma specimens (p < 0.01)." (PMID 26949513, 2016). "It was reported that N,N′-Dinitrosopiperazine (DNP), as substrates of AKR1B10 enzyme, increased the expression of AKR1B10 in nasopharyngeal carcinoma 6-10B cells." (PMID 26949513, 2016). "Taken together, our data suggest that low expression of AKR1B10 is an independent prognostic indicator in nasopharyngeal carcinoma, and that AKR1B10 may be involved in regulating the proliferation and migration of nasopharyngeal cancer cells." (PMID 26949513, 2016). "Therefore, we conclude that AKR1B10 may be used as a prognostic marker for nasopharyngeal carcinoma." (PMID 26949513, 2016). "However, the BRCA and HNSC (including oral cancer and nasopharyngeal cancer) didn’t show significant alterations in AKR1B10 expression, which suggests the analysis with a refined cancer subtype may be helpful to clarify the AKR1B10 expression in special pathological conditions." (PMID 39712017, 2024). "Our data demonstrates that AKR1B10 may be involved in regulating the proliferation and migration of nasopharyngeal cancer cells, and AKR1B10 expression levels are negative correlated with lymph node metastasis of nasopharyngeal carcinoma." (PMID 26949513, 2016).
psoriasis (7 papers, 2015 to 2025). An autoimmune condition characterized by red, well-delineated plaques with silvery scales that are usually on the extensor surfaces and scalp. "We then validated the expression pattern of AKR1B10 in psoriasis and its association with the disease using immune cell infiltration analysis, scRNA-seq, and ST." (PMID 40735022, 2025). "SAMHD1, C10orf99, and AKR1B10: the highly dysregulated genes in resolved epidermis are known to be associated with pathogenesis of psoriasis, and the DRTP was enriched in WNT, TNF, and mTOR signaling pathways." (PMID 36901987, 2023). "This strongly suggests that AKR1B10 promotes a pro-inflammatory immune microenvironment that sustains psoriasis inflammation." (PMID 40735022, 2025). "In the validation dataset, AKR1B10 was consistently differentially expressed in psoriasis samples compared to healthy controls, with statistically significant differences observed." (PMID 40735022, 2025). "Two of these transcripts, C10orf99 and AKR1B10, were highly expressed in the lesional skin of psoriasis patients compared to healthy controls." (PMID 36901987, 2023). "AKR1B10 plays a role in psoriasis lesion formation by dysregulating the retinoic acid signaling pathway, thereby inducing the excessive proliferation of keratinocytes." (PMID 36901987, 2023). "Overexpression of AKR1B10 has been reported in patients with psoriasis, atopic dermatitis and keloids." (PMID 36901987, 2023). "Psoriasis and keloid lesions show extremely high AKR1B10 expression levels (23-86-fold higher than normal skin)." (PMID 34063865, 2021). "The up-regulation of AKR1B10 has been observed in skin lesions of patients with psoriasis, keloids, atopic dermatitis, and type 2 reaction leprosy." (PMID 34063865, 2021). "Currently, AKR1B10 is rarely reported to be related to psoriasis and is only shown to play an important role in liver carcinogenesis and eating behavior." (PMID 29204449, 2017). "We used an RNA interference experiment to further investigate the role of the AKR1B10 gene in the development and progress of psoriasis." (PMID 29204449, 2017). "Our study provided a comprehensive analysis of the expression pattern of psoriasis, revealed the function and pathway change of psoriasis, and further validated the proliferation and migration functions of a candidate biomarker (i.e., AKR1B10)." (PMID 29204449, 2017). "In vitro experiments have demonstrated that silencing AKR1B10 effectively suppresses excessive proliferation and migration of HaCaT cells, further highlighting the potential therapeutic value of this target in psoriasis treatment." (PMID 40735022, 2025). "This suggests that XYJDY-medicated serum may exert its anti-psoriasis effect through inhibition of AKR1B10." (PMID 40735022, 2025). "AKR1B10 was identified as the core therapeutic target of XYJDY in psoriasis." (PMID 40735022, 2025). "Our study demonstrated not only the dysfunction of the AKR1B10 gene in lipid metabolizing but also its important role in the overproliferation and migration of keratinocyte, which provided evidence for further therapeutic uses for psoriasis." (PMID 29204449, 2017). "Importantly, although AKR1B10 has been previously recognized as a key regulatory molecule in the onset and progression of inflammatory diseases, including psoriasis, our study provides substantial new evidence that establishes it as a core functional target of XYJDY." (PMID 40735022, 2025). "Finally, in vitro experiments were conducted using XYJDY-containing serum to intervene in the IL-17A-induced HaCaT cell psoriasis-like inflammation model, confirming the impact of XYJDY on AKR1B10 expression." (PMID 40735022, 2025). "Furthermore, an IL-17A-induced psoriasiform inflammation model in HaCaT keratinocytes demonstrated that XYJDY markedly suppressed AKR1B10 expression, reinforcing its candidacy as a pivotal therapeutic target in XYJDY-mediated treatment of psoriasis." (PMID 40735022, 2025).
psoriasis (continued). "We revealed 479 differentially expressed genes between secukinumab and Dead Sea climatotherapy at the end of treatment, with a psoriasis panel identifying SERPINB4, SERPINB13, IL36G, IL36RN, and AKR1B10 as upregulated in Dead Sea climatotherapy compared with secukinumab." (PMID 38892277, 2024). "Notably, AKR1B10, AKR1B15, and several members of the PLA2 gene family were significantly overexpressed in psoriasis lesion tissue." (PMID 29204449, 2017). "Of the most psoriasis-specific DEGPs, the majority were induced by IL-17A (e.g., FERMT1, GLUL, SULT2B1); in contrast, the most non-specific DEGPs were not disproportionately induced by IL-17A and several were repressed (e.g., AKR1B10, RNF213, ISG15)." (PMID 26251673, 2015). "Thus, genes controlling the turnover of vitamin D (CYP27B1, CYP24A1), vitamin A (ALDH1A3, AKR1B10), and cholesterol (CYP7B1), were up-regulated in psoriasis, whereas melanomas showed downregulation of genes regulating turnover of vitamin A (AKR1C3), and cholesterol (CYP39A1)." (PMID 26901218, 2016). "The observed downregulation of AKR1B10 provides crucial experimental support for our computational predictions and pharmacological hypotheses, suggesting that XYJDY can effectively regulate the expression of this critical target in a psoriasis-like inflammation model." (PMID 40735022, 2025).
bladder cancer (6 papers, 2021 to 2025). "Further, the downregulation of AKR1B10 deactivates ERK activation in bladder cancer via CBX7." (PMID 39001490, 2024). "Similar to our results, overexpression of AKR1B10 induced urinary bladder cancer cell aggressiveness, whereas inhibition of AKR1B10 by siRNA or oleanolic acid could exert the opposite effects." (PMID 36028503, 2022). "In bladder cancer, CBX7 inhibits the Aldo-keto reductase family 1 member B10 and subsequently stimulates Extracellular Signal-Regulated Kinase signaling, thereby suppressing bladder cancer progression." (PMID 39988672, 2025). "Huang et al27 revealed that AKR1B10 was highly expressed in bladder cancer tissues and modulated the proliferation, migration, invasion, and cell stemness of bladder cancer cells through the CUX7/AKR1B10/ERK signaling pathway." (PMID 37823316, 2023).
Hepatic fibrosis (6 papers, 2020 to 2024). The presence of excessive fibrous connective tissue in the liver. "Plasma AKR1B10 alone and in combination with C3 could be a useful noninvasive biomarker for the diagnosis of NASH and hepatic fibrosis." (PMID 35563425, 2022).
inflammatory bowel disease (5 papers, 2017 to 2024). A spectrum of small and large bowel inflammatory diseases of unknown etiology. "In inflammatory bowel disease, the loss of AKR1B10 correlates with chronic colitis and the development of colitis-related carcinoma." (PMID 30320113, 2018). "AKR1B10 a (NADPH)-dependent reductase is highly expressed in the epithelial cells of the stomach and intestine but downregulated in gastrointestinal cancer and inflammatory bowel disease." (PMID 39872609, 2024).
leprosy (5 papers, 2018 to 2024). Leprosy is a chronic infectious disease affecting primarily the skin and peripheral nervous system. "In several samples, AKR1B10 was expressed in the neural branches that were involved in leprosy-associated inflammatory processes." (PMID 30320113, 2018). "As an example, AKR1B10 is a gene overexpressed in different neoplasms, with special importance in pancreatic duct carcinoma, but also expressed in leprosy reactions." (PMID 38440733, 2024). "In a genome-wide study of mRNA expression in leprosy, mRNA of AKR1B10 was observed to be overexpressed in T2R lesions." (PMID 32373110, 2020). "Further immunohistochemistry investigation confirmed the overexpression of AKR1B10 in T2R and showed that AKR1B10 was principally expressed by macrophage in leprosy lesions." (PMID 32373110, 2020). "In summary, AKR1B10 is expressed in the skin lesions of patients with leprosy, predominantly in lepromatous lesions that are in regression, especially those that are associated with R2." (PMID 30320113, 2018). "Thus, AKR1B10 is overexpressed on the lepromatous side (BL and LL) in samples that are in regression, especially type 2 reaction-associated lesions, rendering it a potential marker of type 2 reactional episodes of leprosy and a target of drugs against reactional episodes." (PMID 30320113, 2018). "In normal tissues and neoplasms, AKR1B10 is expressed in various types of cells—primarily epithelial lineage cells—whereas in leprosy, it is expressed in macrophages." (PMID 30320113, 2018). "Recently, we reported that AKR1B10 was overexpressed in skin biopsies of patients with leprosy, especially those with the type 2 reaction." (PMID 30320113, 2018). "The aim of this study was to examine the expression of AKR1B10 in leprosy skin lesions by immunohistochemistry (IHC) and identify the cells in granulomas and skin tissue that express this marker." (PMID 30320113, 2018). "For example, HLA genes (e.g., HLA-B15) are associated with RR, and aldo-keto reductase family 1 member B10 (AKR1B10) is also expressed in patients with ENL and may be a potential marker or target of the leprosy response." (PMID 38440733, 2024). "AKR1B10 is also expressed in type 2 reaction leprosy patients (R2)." (PMID 30320113, 2018). "There is little information on the function of AKR1B10 in leprosy." (PMID 30320113, 2018). "The regulation of mRNA expression by miRNAs is complex, and there are also other mechanisms of epigenetic regulation of gene expression, necessitating further studies to determine whether there is an interaction between hsa-miR-142-3p and AKR1B10 in leprosy." (PMID 30320113, 2018). "Further studies should determine whether AKR1B10 is important for triggering the R2 reaction and whether it can be used as a marker or therapeutic target for the prevention and clinical management of R2 episodes of leprosy." (PMID 30320113, 2018). "Due to the unknown function of AKR1B10 in leprosy, the authors could not determine whether AKR1B10 overexpression was an event accompanying T2R or contributed to T2R development." (PMID 32373110, 2020).
Obesity (5 papers, 2014 to 2023). Accumulation of substantial excess body fat. "Using this approach we have identified the nuclear hormone receptor PPARG, the metalloproteinase ADAMTS5, and the aldo-keto reductase AKR1B10 as potential drug targets for treatment of osteoporosis and obesity." (PMID 27562730, 2016). "The Venn diagram showed that there are indeed common DEGs between obesity and asthma, namely IL36RN, PHACTR3, SLAMF7, AKR1B10 and RNF182." (PMID 37723557, 2023).
oral squamous cell carcinoma (5 papers, 2021 to 2024). "Oral squamous cell carcinoma patients with a high level of AKR1B10 in the saliva are often related to poor prognosis and progression." (PMID 37884970, 2023). "The finding that AKR1B10 expression was correlated with tumor size was consistent with the previously reported expression of AKR1B10 in oral squamous cell carcinoma and breast cancer." (PMID 34521883, 2021).
Barrett esophagus (4 papers, 2012 to 2023). Esophageal lesion lined with columnar metaplastic epithelium which is flat or villiform. "AKR1B10 was shown to be upregulated not only in cancers but also in some preneoplastic conditions, such as Barrett’s esophagus and squamous metaplasia." (PMID 36845547, 2023). "Consistent with our findings, several reports demonstrated AKR1B10 upregulation in some preneoplastic conditions such as squamous metaplasia and Barrett’s esophagus." (PMID 24747592, 2014). "AKR1B10 expression is increased in epithelium specimens from patients with erosive gastro-esophageal reflux disease and Barrett’s esophagus but not in those with esophageal adenocarcinoma." (PMID 34063865, 2021).
endometrial cancer (4 papers, 2017 to 2021). Primary or metastatic malignant neoplasm involving the endometrium (mucous membrane that lines the endometrial cavity). "The roles of aldo-keto reductase family 1 member B1 (AKR1B1) and B10 (AKR1B10) in the pathogenesis of many cancers have been widely reported but only briefly studied in endometrial cancer." (PMID 34298614, 2021). "Immunohistochemical analysis has detected AKR1B10 expression in 20.0% and 15.8% of cervical and endometrial cancer cases, respectively." (PMID 34063865, 2021). "In subsequent studies on endometrial cancer, the expression of AKR1B10 at the mRNA level was significantly increased, while there were significantly decreased protein levels." (PMID 34063865, 2021). "Differences in the expression of AKR1B10 among these studies might be explained by the type of cancer cells, as cervical and endometrial cancers are squamous cell carcinomas and adenocarcinomas, respectively." (PMID 34063865, 2021).
Hepatic steatosis (4 papers, 2014 to 2025). Steatosis is a term used to denote lipid accumulation within hepatocytes. "Interestingly, the present study showed a significant association between AKR1B10 expression in NTs and hepatic steatosis: a cytological change marked by clear vacuoles because of fat accumulation in hepatocytes." (PMID 24747592, 2014). "However, the other liver steatosis gene markers, such as Thbs2, Lum, Lamc3, Lama2, Akr1b10, Col4a4, A2m, and C7, were not significantly different between the db-HF and db-HC groups." (PMID 38613031, 2024).
squamous cell carcinoma (4 papers, 2016 to 2021). A carcinoma arising from squamous epithelial cells. "The top hypomethylated and up-regulated gene, aldo-keto reductase family 1 member B10 (AKR1B10), has been demonstrated previously to be specifically up-regulated in smoking-associated cancers such as squamous cell carcinoma and adenocarcinoma." (PMID 29169318, 2017). "AKR1B10 has been proposed as a promising new diagnostic marker in NSCLC of smokers since it is often overexpressed inmoderate or poorly differentiated NSCLC (in 84% of squamous cell carcinomas and in 29% of adenocarcinomas), mostly in males and smokers." (PMID 27081700, 2016). "AKR1B10 expression is increased in NPC tissues (compared to the normal tissues), in which squamous cell carcinomas show higher AKR1B10 expression than basal cell carcinomas, adenoid cystic carcinomas, adenocarcinomas, and undifferentiated carcinomas." (PMID 34063865, 2021). "Since high expression of AKR1B10 has been observed in an esophageal squamous cell carcinoma cell line, OE-21, it would be interesting to analyze the expression of AKR1B10 in specimens from patients with squamous cell carcinoma, which is the predominant form of esophageal carcinoma worldwide." (PMID 34063865, 2021). "More than 90% of oral cancers are squamous cell carcinomas (OSCC), in which AKR1B10 is overexpressed." (PMID 34063865, 2021).
ulcerative colitis (4 papers, 2021 to 2024). An inflammatory bowel disease involving the mucosal surface of the large intestine and rectum. "However, AKR1B10 silencing in culture cells enhanced carbonyl induced protein and DNA damage; and in ulcerative colitis tissues, AKR1B10 deficiency was associated acrolein-protein lesions." (PMID 38370384, 2024). "Our work suggests that AKR1B8, i.e., AKR1B10 in humans, may participate in development and progression of colitis, being a potential target for clinical management of ulcerative colitis." (PMID 36518763, 2022).
breast tumor (3 papers, 2023 to 2024). "The expression of AKR1B10 correlated positively with breast tumor size and nodal metastasis and inversely with disease-free survival (DFS)." (PMID 39055885, 2024). "AKR1B10 is also overexpressed in infiltrating and recurrent breast tumors." (PMID 39055885, 2024). "Tissue microarray analysis revealed overexpression of AKR1B10 in 84% of breast tumors." (PMID 39055885, 2024). "Further, AKR1B10 expression was significantly increased in postmenopausal breast tumors, while AKR1B1 was not altered." (PMID 39055885, 2024). "AKR1B10 induces PI3K/Akt signaling, stimulates the NF‐κB pathway, promotes the expression levels of ZEB1, Slug, and Twist in EMT induction, and increases the migration rate of breast tumor cells." (PMID 37688511, 2023).